G3BP1 (G3BP stress granule assembly factor 1)
Diseases named in the same sentence as G3BP1 in open-access papers (continued):
Sharing a sentence is not in itself a finding about the gene and the disease.
osteosarcoma (18 papers, 2016 to 2025). A usually aggressive malignant bone-forming mesenchymal neoplasm, predominantly affecting adolescents and young adults. "In vivo, SGs have been implicated in metastasis, as osteosarcoma cells with knockdown of G3BP1 were associated with reduced levels of lung metastases upon implantation in the kidney capsule, compared to control osteosarcoma cells, which formed lung metastases within 4-5 weeks of implantation." (PMID 35147163, 2022). "TCGA data analysis revealed that G3BP1 and AEP are highly expressed in tumor tissues and is significantly associated with poor prognosis in glioma and osteosarcoma." (PMID 40858563, 2025). "To identify RNAs within the SG cores in SH-SY5Y cells, we purified the cores by immunoprecipitation (IP) with an anti-G3BP1 antibody according to a previously reported procedure, in which human osteosarcoma U2OS cells were used." (PMID 37219408, 2023). "This would explain why VF formation coincides with SG disruption and why MRV replicates to higher titers in G3BP1/2 knockout human osteosarcoma U2OS cells, which cannot form SGs, compared to wild-type U2OS cells." (PMID 33525628, 2021). "In our study, the expression of G3BP1 decreased in the LG compared with the CG and increased in rhIL-6-pretreated osteosarcoma cells compared with tumor cells treated with lobaplatin alone." (PMID 33791202, 2021). "When we compared G3BP1-associated transcripts to two recently published SG-transcriptomes, we found only 2% similarity of our G3BP1-associated mRNAs with the first study, which was conducted using arsenite treatment using U2OS osteosarcoma cells." (PMID 32406909, 2020). "SIN-1 induces the formation of SGs in U2OS osteosarcoma cells as analyzed by colocalization of G3BP1 and TIA-1, two canonical SG markers." (PMID 30425239, 2018). "This interaction highlights how YB-1 may modulate the expression of G3BP1, influencing the invasive capabilities and overall aggressiveness of osteosarcoma cells." (PMID 39497723, 2024). "In addition, when G3BP1, the critical SG effector protein, is knocked down in osteosarcoma cells and then implanted in mice, there are decreased SGs and metastasis compared to wild-type cells." (PMID 33525628, 2021). "siRNAs were synthesized to separately silence the three genes, G3BP1, FUBP1, and FXR1, and the sensitivity of osteosarcoma cells to lobaplatin were detected." (PMID 33791202, 2021). "To study potential proviral roles of G3BP, we used human osteosarcoma (U2OS) cell lines lacking endogenous G3BP generated using CRISPR-Cas9 and reconstituted with a panel of G3BP1 mutants and truncation variants." (PMID 31199850, 2019). "In addition to U2OS osteosarcoma cells, CisPt potently induces G3BP1-positive, eIF4g and eIF3b- negative foci in other cancer cell lines (including HeLa (cervix), MES-SA (uterus) and SiHa (cervix)) under similar doses." (PMID 34864307, 2022). "Using the SG-specific marker G3BP1, we tested whether platinum-based drugs such as CisPt, oxaliplatin (OxaPt) and carboplatin (CrbPt) also stimulate formation of G3BP1-positive cytoplasmatic foci as sodium arsenite (SA) and vinorelbine (VRB) in human osteosarcoma U2OS cells." (PMID 34864307, 2022). "In infected cells (human osteosarcoma U2OS cell line), NCoV2 phase-separates into condensates with RNA and the stress granule core protein G3BP1, but not with other stress granule proteins, suggesting that NCoV2 suppresses the G3BP1-dependent host immune system." (PMID 34064163, 2021).
hepatocellular carcinoma (17 papers, 2018 to 2025). A malignant tumor that arises from hepatocytes. "Supporting this mechanism, we observed markedly elevated levels of phosphorylated G3BP1 (P-G3BP1) in melanoma cell lines compared to hepatocellular carcinoma (HepG2, Hep3B) and pancreatic carcinoma (Panc-1) cell lines." (PMID 41148289, 2025). "The “writer” NSUN2 modifies the lncRNA H19 and recruits the oncoprotein G3BP1 in hepatocellular carcinoma, suggesting that m5C modifications are involved in malignant tumor progression." (PMID 37666951, 2023). "More recently, the overexpression of G3BP1 has been implicated in human cancers, including breast, gastric, colon, and liver carcinomas, suggesting the oncogenic and functional role of G3BP1 in tumorigenesis." (PMID 29717134, 2018). "reveled that NSUN2, an m5C methyltransferase, is significantly upregulated in hepatocellular carcinoma (HCC), and it promotes tumor progression by catalyzing the H19 lncRNA methylation-mediated recruitment of the G3BP1 oncoprotein." (PMID 36777349, 2023). "In hepatocellular carcinoma, NSUN2 affects the biological function of hepatocellular carcinoma cells and methylates lncRNA H19RNA and methylated H19 recruits oncogene G3BP1 to promote the occurrence and development of tumors." (PMID 35574373, 2022). "In hepatocellular carcinoma (HCC), both the H19 lncRNA and m5C methylation are increased, which is significantly related to m5C-induced H19 lncRNA expression and is uniquely connected to the Ras-GTPase-activating protein SH3 domain-binding protein 1 (G3BP1)." (PMID 38871819, 2024).
renal cell carcinoma (14 papers, 2018 to 2026). "G3BP1 also causes tumor progression and metastasis in renal cell carcinoma cells by over-expression along the IL6 / G3BP1 / STAT3 pathway." (PMID 34604242, 2021). "Evidence shows that G3BP1 promotes tumour progression and metastasis through the IL-6/G3BP1/STAT3 signalling axis in renal cell carcinoma." (PMID 33579337, 2021). "The levels of G3BP1, which plays a critical role in stress granule (SG) formation, are increased in renal cell carcinoma (RCC) and promote IL6/STAT3 activation." (PMID 31952344, 2020). "In addition, the complex composed of YBX1 and G3BP1 plays a crucial role in enhancing NF-κB promoter activity and promoting the metastasis of renal cell carcinoma." (PMID 41513625, 2026). "In addition to inducing metastasis in EOC, G3BP1 induces metastasis through IL-6/G3BP1/STAT3 signaling in renal cell carcinoma." (PMID 37107644, 2023). "Moreover, a study has reported that the YBX1/G3BP1 complex could activate the downstream NF-κB signaling pathway in renal cell carcinoma cells." (PMID 41513625, 2026). "G3BP1 contributes to the proliferation, migration and invasion of renal cell carcinoma (RCC), and knockdown of G3BP1 blocks the IL-6/STAT3 signaling and reduces the metastatic ability of RCC." (PMID 34526993, 2021). "Our previous research has demonstrated that YBX1 interacts with G3BP1 to upregulate its downstream protein SPP1 expression, thereby activating the NF-κB signaling pathway and thus promoting renal cell carcinoma (RCC) metastasis." (PMID 36330442, 2022). "Similarly, in renal cell carcinomas, G3BP Stress Granule Assembly Factor 1 (G3BP1) has been shown to promote tumor progression and metastasis." (PMID 34827123, 2021).
gastric cancer (11 papers, 2019 to 2025). A primary or metastatic malignant neoplasm involving the stomach. "G3BP1 was associated with the poor outcome of gastric cancer patients who received adjuvant chemotherapy." (PMID 32989225, 2021). "The results showed that high G3BP1 expression was significantly associated with poor OS and progression-free survival of gastric cancer patients in the cohort who received postoperative chemotherapy, but not in the surgery-alone group." (PMID 32989225, 2021). "Importantly, re-introduction of G3BP1 in gastric cancer cells could efficiently rescue G3BP1-deficiency-reduced tumorigenesis, indicating that G3BP1 plays an important role in the chemoresistance of gastric cancer cells both in cells and in vivo." (PMID 32989225, 2021). "In other malignant tumors, G3BP1 was thought to play the oncogenic roles such as gastric cancer 12, 47-49, prostate cancer 50, 51, esophageal cancer 10, ovarian cancer 52, 53 and colorectal cancer." (PMID 38164170, 2024). "Meanwhile, knockdown of YWHAZ or Bax had little effect on SGs formation in gastric cancer cells, which indicates that G3BP1/YWHAZ/Bax pathway exerts anti-apoptosis and chemoresistance roles in gastric cancer via an SG-independent mechanism." (PMID 32989225, 2021). "The influence of G3BP1 on gastric cancer cell chemoresistance and apoptosis were evaluated by in vitro and in vivo approaches." (PMID 32989225, 2021). "We then analysed the G3BP1 expression level in gastric cancer samples (n = 455) from Zhongshan Hospital." (PMID 32989225, 2021). "Kaplan–Meier analysis was used to compare survival rates in gastric cancer patients with different G3BP1 expression." (PMID 32989225, 2021). "Taken together, in this study, G3BP1 was revealed to govern gastric cancer apoptosis and to play a pivotal role in gastric cancer chemoresistance through mediating SGs formation or via an SG-independent mechanism: the G3BP1/YWHAZ/Bax axis." (PMID 32989225, 2021). "Collectively, these results suggest that in response to anti-cancer drug treatment, G3BP1 confers gastric cancer chemotherapeutic resistance through inhibiting cellular apoptosis." (PMID 32989225, 2021). "Taken together, these observations suggest that high G3BP1 expression can predict or influence the response of gastric cancer patients to chemotherapy." (PMID 32989225, 2021). "G3BP1 knockdown significantly increased the sensitivity of gastric cancer cells to chemotherapy drugs." (PMID 32989225, 2021). "We next examined the expression of apoptotic-related factors and found that pro-apoptotic markers (cleaved PARP, cleaved caspase-9, cleaved caspase-3 and Bax) were markedly elevated in G3BP1-compromised gastric cancer cells." (PMID 32989225, 2021). "Then, we investigated the correlation between YWHAZ expression and G3BP1 expression in human gastric cancer samples." (PMID 32989225, 2021). "Lower expression of G3BP1 increases the chemotherapy sensitivity in gastric cancer cells and predicts favourable benefits of chemotherapy and prognosis for patients with gastric cancer." (PMID 34802443, 2021). "In our study, we found that high G3BP1 expression was markedly correlated with poor survival of gastric cancer patients who received ACT and revealed a potent oncogenic role for G3BP1 in apoptosis inhibition and chemoresistance in gastric cancer." (PMID 32989225, 2021). "The IHC results showed that G3BP1 protein expression was noticeably higher in gastric cancer tissues than in adjacent normal tissues." (PMID 32989225, 2021). "Further investigation showed that YWHAZ was positively correlated with G3BP1 expression in gastric cancer patients and that high expression of both G3BP1 and YWHAZ was associated with the worst prognosis in gastric cancer patients who received ACT." (PMID 32989225, 2021).
gastric cancer (continued). "We found that G3BP1 mRNA levels were positively correlated with YWHAZ mRNA levels in gastric cancer patients by data mining the TCGA database (n = 233, r = 0.379, P < 0.001) and the GEO database (n = 80, r = 0.503, P < 0.001)." (PMID 32989225, 2021). "To validate our observation that G3BP1 is positively correlated with gastric cancer chemotherapy, we performed an integrated microarray dataset-based analysis of the GSE14210, GSE15459, GSE22377, GSE29272, GSE51105 and GSE62254 datasets." (PMID 32989225, 2021). "Our findings not only provide an improved prognostic marker for gastric cancer chemoresistance but also suggest a potential strategy to target G3BP1 for sensitising gastric cancer to chemotherapy." (PMID 32989225, 2021). "Noteworthy implications of G3BP1 extend to breast, colon, esophageal, and gastric cancer 9-12." (PMID 38164170, 2024). "Moreover, recent evidence suggests that G3BP1 inhibits gastric cancer cell apoptosis via the YWHAZ/Bax axis." (PMID 37179344, 2023). "Importantly, high G3BP1 expression was positively associated with tumour progression, lymph node metastasis, advanced TNM stage and vascular invasion in gastric cancer patients." (PMID 32989225, 2021). "Subsequently, we detected the mRNA levels of Bax in MGC80-3 cells and found that G3BP1 could significantly reduce the mRNA abundance and mRNA half-life of Bax in gastric cancer cells." (PMID 32989225, 2021). "Moreover, upon treatment of capecitabine or oxaliplatin, ectopically expressed G3BP1 greatly increased, whereas depletion of G3BP1 decreased the colony-forming ability of gastric cancer cells compared to that of parental cells." (PMID 32989225, 2021). "Further mechanistic exploration revealed that G3BP1 could inhibit pro-apoptotic Bax mRNA expression and suppress apoptosis in gastric cancer cells treated with chemotherapy." (PMID 32989225, 2021). "In addition, we found through a gene co-expression analysis that G3BP1 could be co-expressed with YWHAZ in gastric cancer." (PMID 32989225, 2021). "We found that G3BP1 depletion and capecitabine treatment had synergistic effects in markedly reducing subcutaneous tumour growth compared to that in the control group, indicating that shG3BP1 gastric cancer cells were likely more sensitive to chemotherapy following capecitabine treatment." (PMID 32989225, 2021). "One study found that G3BP1 interacts with YWHAZ to isolate Bax in the cytoplasm, thereby enhancing chemotherapy resistance in gastric cancer." (PMID 37179344, 2023). "For example, G3BP1 has an interaction with YWHAZ and further sequesters Bax into the cytoplasm, contributing to anti-apoptosis and drug resistance of gastric cancer." (PMID 34967276, 2022). "Our mechanistic exploration showed that G3BP1 co-localised with YWHAZ in the cytoplasm and physiologically interacted with YWHAZ in gastric cancer cells." (PMID 32989225, 2021). "Further analysis of Zhongshan cohort patients by IHC staining demonstrated that the protein expression of G3BP1 and that of YWHAZ were also positively correlated in human gastric cancer (n = 455, r = 0.464, P < 0.001)." (PMID 32989225, 2021). "Here, we found that G3BP1 had prognostic and predictive value regarding ACT benefits in patients with gastric cancer." (PMID 32989225, 2021). "As an SG assembly effector, G3BP1 (Ras-GTPase-activating protein SH3 domain-binding protein) has been reported to be overexpressed in gastric cancer; thus, here we aim to explore its potent roles in gastric cancer chemoresistance." (PMID 32989225, 2021). "After depleting G3BP1 in gastric cancer cells, we examined the IC50 values of these two drugs in suppressing gastric cancer cell growth and observed that depletion of G3BP1 markedly decreases the IC50 values of both capecitabine and oxaliplatin in gastric cancer cells." (PMID 32989225, 2021).
gastric cancer (continued). "To address the molecular mechanisms by which the co-expression and co-operative function of G3BP1 and YWHAZ act in gastric cancer, we initially performed immunofluorescence assay to detect the intracellular localisation of G3BP1 and YWHAZ in gastric cancer cells." (PMID 32989225, 2021). "The expression of G3BP1 and YWHAZ could predict the adjuvant chemotherapy benefit in gastric cancer patients." (PMID 32989225, 2021). "Therefore, we speculated that G3BP1 co-expression and binding with YWHAZ could modulate the interaction between YWHAZ and Bax in gastric cancer cells." (PMID 32989225, 2021). "By analysing microarray datasets from the Gene Expression Omnibus (GEO) and the Cancer Genome Atlas (TCGA) database, we found that the mRNA level of G3BP1, but not that of family member G3BP2, was significantly higher in human gastric cancer samples than in normal tissue samples." (PMID 32989225, 2021).
sarcoma (11 papers, 2019 to 2023). A usually aggressive malignant neoplasm of the soft tissue or bone. "Moreover, elevated G3BP1 expression correlates with poor survival in human sarcomas, where YB-1 and G3BP1 expression is tightly associated." (PMID 32406909, 2020). "For example, the Y-box binding protein 1 (YB-1) interacts with the 5'-untranslated region (UTR) of G3BP1, leading to the increased expression of G3BP1 and SGs, which is elevated in human sarcomas." (PMID 38110976, 2023). "Researchers found that the SG-associated protein YB-1 mediated SG assembly by binding to the 5′ UTR of G3BP1 mRNA, thus promoting sarcoma invasion and metastasis." (PMID 36291863, 2022). "MS-275 treatment enhances YB-1 acetylation and lowers deacetylation, prevents the binding of factors such as HIF1a and G3BP1 to its mRNA, suppresses pro-metastatic activity via reducing YB-1 translation, and reduces sarcoma metastasis." (PMID 35004322, 2021). "Remarkably, the reduction of G3BP1 levels through YB-1 globally acetylation by MS-275 treatment reduces the sarcoma metastasis and reduces the premetastatic activity of the G3BP1 factor." (PMID 34604242, 2021). "YB-1 inactivation in human sarcoma cells dramatically reduced G3BP1 levels and SG formation, and G3BP1 inactivation in sarcoma xenografts prevented in vivo SG formation, local tumor invasion, and lung metastasis in mouse models." (PMID 32406909, 2020). "YBX1 and Ras-GTPase activating protein SH3 domain binding proteins 1 (G3BP1) were reported to exhibit highly correlated expression levels in sarcomas." (PMID 31481087, 2019). "In addition, we have also demonstrated that YB-1 regulates stress granule formation and tumour progression in sarcomas by translationally activating G3BP1 and SG formation." (PMID 34294889, 2022). "Translation and synthesis of NRF2, as well as of other known YB‐1 targets, G3BP1 and HIF1α, were blocked by MS‐275 in sarcoma cells, due to enhanced acetylation of lysine 81 within the YB‐1 RNA‐binding domain and consequent loss of YB‐1 translational activation of these stress factors." (PMID 31668005, 2019). "In human sarcoma, the Y-box binding protein 1 (YB1) enhances the formation of SGs by binding directly to G3BP1’s 5’UTR and promoting G3BP1 mRNA translation, thus enhancing the invasion and metastasis of human sarcoma cell." (PMID 37179344, 2023). "MS‐275 dramatically reduces sarcoma metastasis in vivo, but an MS‐275‐resistant YB‐1K81‐to‐alanine mutant restores metastatic capacity and NRF2, HIF1α, and G3BP1 synthesis in MS‐275‐treated mice." (PMID 31668005, 2019).
colon carcinoma (10 papers, 2013 to 2025). "G3BP1 is significantly upregulated in colon cancer tissues and its high expression is closely associated with poor prognosis and clinical progression of colon cancer patients." (PMID 36330442, 2022). "Peptide analog GAP161, which targets G3BP1, has been proven to suppress colon carcinoma development." (PMID 40214262, 2025). "Among them, GAP161 can improve the sensitivity of colon cancer cells to cisplatin by down-regulating G3BP1." (PMID 37904149, 2023). "Both vitro and vivo studies demonstrated that G3BP1 inhibits apoptosis in colon cancer cell and promotes colon cancer progression by activating the β-catenin signaling pathway." (PMID 37179344, 2023). "This is in line with findings that downregulated levels of G3BP1 lead to suppressed growth in colon carcinoma cells and that mice with G3BP1 gene deletion have decreased fetal growth and higher embryonic lethality." (PMID 24321297, 2013).